FZD6 (frizzled class receptor 6)
Description:
Receptor for Wnt proteins. Most of frizzled receptors are coupled to the beta-catenin canonical signaling pathway, which leads to the activation of disheveled proteins, inhibition of GSK-3 kinase, nuclear accumulation of beta-catenin and activation of Wnt target genes. A second signaling pathway involving PKC and calcium fluxes has been seen for some family members, but it is not yet clear if it represents a distinct pathway or if it can be integrated in the canonical pathway, as PKC seems to be required for Wnt-mediated inactivation of GSK-3 kinase. Both pathways seem to involve interactions with G proteins. May be involved in transduction and intercellular transmission of polarity information during tissue morphogenesis and/or in differentiated tissues. Together with FZD3, is involved in the neural tube closure and plays a role in the regulation of the establishment of planar cell polarity (PCP), particularly in the orientation of asymmetric bundles of stereocilia on the apical faces of a subset of auditory and vestibular sensory cells located in the inner ear (By similarity).
Synonyms: Fz-6; hFz6; FZ6; NDNC1; NDNC10
Tractability: Antibody: its Gene Ontology location is reachable by antibodies, with high confidence; UniProt places it where antibodies can reach, with medium confidence; UniProt predicts a signal peptide or a membrane-spanning region; the Human Protein Atlas places it where antibodies can reach. PROTAC: UniProt records ubiquitination sites on it; ubiquitination databases record sites on it.
Gene: Protein-coding gene on chromosome 8 (103,298,433 to 103,332,866, forward strand). Ensembl gene ENSG00000164930.
Subcellular location: Membrane; Cell membrane; Cell surface; Apical cell membrane; Cytoplasmic vesicle membrane; Endoplasmic reticulum membrane
Subcellular location (Human Protein Atlas): Plasma membrane; Basal body; Primary cilium
Pathways (Reactome):
Signal Transduction: Ca2+ pathway; Class B/2 (Secretin family receptors); PCP/CE pathway; Regulation of FZD by ubiquitination
Disease: Signaling by RNF43 mutants
Gene Ontology:
Molecular function: protein binding; ubiquitin protein ligase binding; Wnt receptor activity; amyloid-beta binding; Wnt-protein binding; transmembrane signaling receptor activity
Biological process: negative regulation of canonical Wnt signaling pathway; negative regulation of transcription by RNA polymerase II; non-canonical Wnt signaling pathway; canonical Wnt signaling pathway; midbrain morphogenesis; Wnt signaling pathway, planar cell polarity pathway; cell surface receptor signaling pathway
Cellular component: plasma membrane; cell surface; cytoplasmic vesicle membrane; endoplasmic reticulum membrane; membrane; apical part of cell; apical plasma membrane; apicolateral plasma membrane
Genetic constraint (gnomAD): Loss-of-function variants: 35 observed, 38.66 expected, observed/expected ratio (o/e) 0.91, 90% interval 0.69 to 1.2. The upper end of that interval is the gene's LOEUF score, 1.2, which puts it in group 5 of 6, group 1 being the genes least tolerant of losing a copy. Missense variants: 465 observed, 605.05 expected, observed/expected ratio (o/e) 0.77, 90% interval 0.71 to 0.83. Synonymous variants: 182 observed, 211.61 expected, observed/expected ratio (o/e) 0.86, 90% interval 0.76 to 0.97.
Homologues: Orthologues: chimpanzee FZD6 (98% identical), macaque FZD6 (98% identical), dog FZD6 (93% identical), rabbit FZD6 (92% identical), pig FZD6 (91% identical), rat Fzd6 (86% identical), mouse Fzd6 (84% identical), guinea pig FZD6 (79% identical), tropical clawed frog fzd6 (63% identical), zebrafish fzd6 (47% identical). Paralogues in human: FZD3 (49% identical), FZD1 (34% identical), FZD2 (33% identical), FZD7 (33% identical), FZD8 (29% identical), FZD5 (28% identical), FZD10 (27% identical), FZD9 (26% identical), FZD4 (25% identical), SMO (22% identical), FRZB (11% identical), SFRP4 (11% identical), and 3 more.
Diseases named in the same sentence as FZD6 in open-access papers:
FZD6 is named in the same sentence as 74 diseases in open-access papers, as found by Europe PMC text mining. Sharing a sentence is not in itself a finding about the gene and the disease. The quoted sentences say what the papers report.
colorectal cancer (13 papers, 2015 to 2025). A primary or metastatic malignant neoplasm that affects the colon or rectum. "NPTX2 promoted the proliferation and metastasis of colorectal cancer cells through interacting with FZD6." (PMID 33618667, 2021). "Other studies indicated that FZD6 contributes to the metastasis of colorectal cancer and the malignancy of acute myeloid leukemia cells through activating Wnt/β-catenin signaling." (PMID 32174831, 2020). "In the present study, we found NPTX2 expression was upregulated in CRC, which promotes colorectal cancer growth and liver metastasis by the activation of the canonical Wnt/β-catenin pathway via FZD6." (PMID 30833544, 2019). "Collectively, these results show that FZD6 knockdown impairs DNA damage repair, which is consistent with a previous study showing that a pan-Wnt inhibitor that blocks the secretion of Wnt ligands attenuates DNA damage repair in colorectal cancer cells." (PMID 41286306, 2025). "The expression level of FZD6 was strikingly elevated in colorectal cancer." (PMID 37554539, 2023). "The combined expression of WNT11 and FZD6 could be predictive of a worse clinical outcome for patients with colorectal cancer." (PMID 33618667, 2021). "The negative regulation of FZD6 expression by miR-199a-5p has been observed in colorectal cancer." (PMID 33630973, 2021). "Similarly, alterations of several FZD receptors have been in many human cancers and FZD6 has been found to be increased in human liver, prostate, colorectal cancer and cutaneous SCC." (PMID 34072517, 2021). "The study also identifies FZD6, RYK, and PTK7 as candidate receptors for Wnt-11 in colorectal cancer." (PMID 31261741, 2019).
breast cancer (12 papers, 2016 to 2024). A primary or metastatic malignant neoplasm involving the breast. "There are numerous studies show that FZD6 expression is associated with the malignancy and prognosis of breast cancer, cervical cancer and human glioblastoma." (PMID 35859893, 2022). "Ingenuity pathway analysis showing FZD6 is implicated in different types of breast cancer." (PMID 35237656, 2022). "It has also been revealed that the FZD6-fibronectin actin axis can be exploited in drug development for highly metastatic forms of breast cancer." (PMID 35185897, 2022). "MicroRNAs identified by the ingenuity pathway analysis and validated by TargetScan and miRabel for the microRNA target prediction analysis showing the potential microRNAs expressed in different types of breast cancer and potentially targeting FZD6." (PMID 35237656, 2022). "In contrast, in gastric cancer cells where H. pylori increases β-catenin activity, the breast cancer chemoprevention agent tamoxifen combined with 17β-Estradiol increased FZD6 expression and repressed gastric cancer tumorigenesis." (PMID 34604862, 2021). "Ablation of FZD6 expression in human mammary cancer cell lines was found to inhibit cell invasion, lead to a more symmetrical growth pattern and inhibit the metastatic potential of tumorous cells." (PMID 34072517, 2021). "In breast cancer cells, FZD6 expression induces EMT, while knockout of FZD6 inhibits motility and invasiveness." (PMID 34604862, 2021). "In breast cancer cells and in solid autocrine human growth hormone (hGH) tumours, both WNT4 and its receptor FZD6 were upregulated indicating that WNT4 is a strong Wnt ligand candidate to activate FZD6." (PMID 35237656, 2022). "In fact, several tumor suppressor genes such as CASP3, RECK, FZD6, and NKX2 were strongly downregulated in MDA-MB-231 breast cancer cells and exhibited promoter hypermethylation in the canine TNBC samples." (PMID 32051475, 2020). "Our current study aimed to analyse the expression pattern of a number of frizzled receptors in Saudi Arabia breast cancer (BC) tissue and here we present only FRIZZLED6 (FZD6) analysis." (PMID 27454254, 2016). "For example, the roles of integrin and human epidermal growth factor receptor, FZD6 and Malat1 long non-coding RNAs in pretumor tissues have been confirmed, revealing the importance of RANK ligand and JNK in the development of breast cancer and breast cancer." (PMID 38342791, 2024). "The researchers concluded that in highly metastatic forms of breast cancer, such as TNBC, the FZD6-fibronectin actin axis could be targeted for drug treatment." (PMID 31921802, 2019). "In metastatic breast cancer cells induced by stromal Wnt11-containing exosomes, Fzd6 and Vangl1 exhibit mutually exclusive localizations, with Fzd6 on the leading edge of cell protrusions and Vangl1 on non-protrusive cell surfaces, and knock-down of either protein decreases cell motility." (PMID 26990447, 2016).
glioblastoma (11 papers, 2016 to 2026). The most malignant astrocytic tumor (WHO grade IV). "The over expression of FZD6 was reported to be associated with poor prognosis in glioblastoma patients." (PMID 33035235, 2020). "High FZD6 expression has been identified in various cancer cells, including in glioblastoma, oral squamous cell carcinoma, and pancreatic adenocarcinoma, showing a strong correlation with tumor malignancy and prognosis." (PMID 36452482, 2022). "In glioblastoma, two miRNAs, miR-125b and miR-20b, are differentially regulated in proneural and mesenchymal glioblastomas and are inversely expressed compared to Fzd6 expression." (PMID 34671643, 2021). "The up-regulation of FZD6 coupled with down-regulation of the transcription factor TCF4 was previously proposed to predict the low survival of glioblastoma patients." (PMID 33630973, 2021). "In agreement with this hypothesis, FZD6 is highly expressed in brain tumours containing mesenchymal, stem-like glioblastoma cells." (PMID 28737757, 2017). "Confirming the findings of the activation screen, overexpression of either canonical (CTNNβ1) or non-canonical (FZD6) genes of the Wnt pathway confers resistance to TMZ treatment in glioblastoma cells." (PMID 33271924, 2020).
prostate carcinoma (11 papers, 2018 to 2025). A carcinoma that arises from epithelial cells of the prostate gland. "Collectively, these data show that FZD6 expression is increased during prostate cancer progression and associate with worse outcome." (PMID 41286306, 2025). "Collectively, we demonstrate that targeting a single FZD receptor highly expressed in prostate cancers can yield significant therapeutic efficacy, and uncover therapeutic vulnerabilities associated with FZD6 inhibition." (PMID 41286306, 2025). "Knockdown of FZD6 suppresses both in vitro and in vivo growth of various prostate cancer cell lines and patient-derived xenograft models." (PMID 41286306, 2025). "Collectively, these results demonstrate that knocking down FZD6 suppresses the growth of aggressive subtypes of prostate cancer." (PMID 41286306, 2025). "We then sought to identify other kinase targets that can cooperate with FZD6 knockdown to inhibit prostate cancer cell growth." (PMID 41286306, 2025). "We show that FZD6 is the most highly expressed and frequently amplified Wnt receptor in advanced human prostate cancers." (PMID 41286306, 2025). "This indicates that targeting a single FZD receptor that is highly expressed in prostate cancer cells is sufficient to achieve therapeutic efficacy, providing strong rationale for the development and application of FZD6-targeted therapies." (PMID 41286306, 2025). "We knocked down FZD6 in multiple prostate cancer cell lines and prostate cancer patient-derived xenograft models and demonstrated that knocking down FZD6 suppresses prostate cancer growth in vitro and in vivo and attenuates the DNA damage repair process." (PMID 41286306, 2025). "To investigate how FZD6 knockdown affects prostate cancer cell growth, we compared the gene expression profiles of DU145 cells that expressed FZD6 shRNAs and scrambled shRNA." (PMID 41286306, 2025). "A kinome-wide CRISPR-Cas9 knockout screen reveals that FZD6 inhibition sensitizes prostate cancer cells to the inhibition of PKMYT1, a WEE kinase family member." (PMID 41286306, 2025). "An alternative strategy for FZD6 inhibition is to conjugate siRNA targeting FZD6 with aptamers directed against prostate cancer antigens such as PSMA (prostate-specific membrane antigen) or TfR1 (Transferrin Receptor 1)." (PMID 41286306, 2025). "Collectively, these results show that targeting FZD6 enhances the therapeutic efficacy of cisplatin in castration-resistant prostate cancer." (PMID 41286306, 2025). "We show that FZD6 is the most highly expressed and amplified frizzled receptors in both AR+ and AR- advanced prostate cancers." (PMID 41286306, 2025). "FZD6 is also consistently expressed in the LuCaP PDX models representing a wide spectrum of prostate cancer genotypes and phenotypes including CRPC, DNPC, and NEPC." (PMID 41286306, 2025). "Luteolin has been found to inhibit Wnt signaling in prostate cancer cells through the transcriptional upregulation of FZD6." (PMID 38474604, 2024). "Further studies have shown that luteolin inhibits Wnt signaling by up-regulating FZD6 to inhibit prostate cancer stemness." (PMID 39840099, 2024). "Comparative proteomics showed that the triterpenoid compound, luteolin, suppressed prostate cancer stemness through the induction of frizzled class receptor 6 (FZD6) expression." (PMID 38203613, 2023). "In prostate cancer, FZD6 is down regulated, leading to an increase in the stem phenotype of prostate cancer cells." (PMID 34604862, 2021). "Collectively, above results demonstrated that luteolin attenuates Wnt signaling via upregulation of FZD6 to suppress prostate cancer stemness." (PMID 29867083, 2018). "FZD7, FZD8, and ROR2 showed the lowest expression in most of the prostate cancer cell lines, while FZD6 and RYK were abundantly expressed." (PMID 29930766, 2018).
prostate carcinoma (continued). "We showed that a negative regulator of β-catenin transcriptional activity, FZD6 (frizzled class receptor 6), is one of the key regulators related to luteolin treatment; it inhibits Wnt signaling pathway and the stemness of prostate cancer cells." (PMID 29867083, 2018). "The expression of FZD6 is significantly downregulated in prostate cancer tissues compared with adjacent normal tissues." (PMID 29867083, 2018). "We also revealed that FZD6, one of the targets of luteolin, plays a tumor suppressive role in prostate cancer." (PMID 29867083, 2018). "We next evaluated whether FZD6 knockdown enhances the therapeutic effect of cisplatin toward advanced human prostate cancers in vivo using the LuCaP35CR CRPC model that we have engineered to express the doxycycline inducible FZD6 shRNA." (PMID 41286306, 2025). "Knockdown of FZD6 enhances the therapeutic efficacy of genotoxic agents for prostate cancer cells." (PMID 41286306, 2025). "Finally, bioinformatic analysis shows that the expression level of FZD6 positively correlates with the Gleason grade of the primary prostate cancer specimens in two independent human prostate cancer datasets." (PMID 41286306, 2025). "This upregulation of FZD6 leads to the suppression of prostate cancer stemness." (PMID 38474604, 2024). "FZD6 is a tumor suppressor that can eliminate prostate cancer stemness." (PMID 39840099, 2024). "Similarly, Luteolin, was known to suppress the stemness of prostate cancer cells by inhibiting the Wnt signaling via transcriptional upregulation of frizzle class receptor 6 (FZD6)." (PMID 33369466, 2020). "As several studies indicated that GSK-3β is one of the targets of luteolin in several types of cancers, we next investigated whether FZD6-mediated inhibitory effect of luteolin is GSK-3β-independent in prostate cancer." (PMID 29867083, 2018). "Furthermore, the mRNA levels of C-Myc, Cyclin D1, CD44 and CD133 were upregulated by FZD6 depletion, which indicated that FZD6 negatively regulates Wnt signaling and inhibits the stemness of prostate cancer." (PMID 29867083, 2018). "Furthermore, our results demonstrated that FZD6-mediated inhibition of Wnt signaling is critical for luteolin suppressing the prostate cancer stemness." (PMID 29867083, 2018). "We first examined the expression of FZD6 in a total of 43 prostate cancer tissues by qRT-PCR." (PMID 29867083, 2018). "Therefore, we reasoned that FZD6 knockdown may sensitize prostate cancer cells to DNA-damaging agents." (PMID 41286306, 2025). "In the present report, we established a proximity ligation assay (PLA) to detect and quantify the co-localization of FZD6 with the major canonical co-receptor LRP6 as an early event of the well-documented Wnt/β-catenin signal transduction after Wnt10B stimulation in PC-3 prostate cancer cells." (PMID 34769487, 2021). "Our study using multiple prostate cancer cell lines and PDX models shows that knocking down FZD6 suppresses prostate cancer cell growth and impairs the DNA-damage repair." (PMID 41286306, 2025). "As FZD6 knockdown downregulated WEE1, we reasoned that FZD6 knockdown may sensitize prostate cancer cells to WEE1 inhibitors." (PMID 41286306, 2025). "To investigate the role of FZD6 in prostate cancer progression, we used 2 shRNAs to knock down FZD6 in 3 representative human prostate cancer cell lines that highly express FZD6: the androgen receptor (AR) negative DU145, androgen-independent but AR-expressing C4-2B and LN95." (PMID 41286306, 2025). "As the role of FZD6 in pathogenesis of prostate cancer has not yet been characterized and to further confirm our finding, we next examined whether FZD6 is a tumor suppressor in PCa and suppresses PCa stemness." (PMID 29867083, 2018). "Prostate cancer cells (PC-3) stimulated by Wnt ligands (Wnt5A, Wnt10B) were analyzed by Cy3-PLA for the co-localization of FZD6 and co-receptors (canonical: LRP6, non-canonical: ROR1) at the single-cell level." (PMID 34769487, 2021).